PDX1 (pancreatic and duodenal homeobox 1)
Diseases named in the same sentence as PDX1 in open-access papers (continued):
Sharing a sentence is not in itself a finding about the gene and the disease.
pancreatic cancer (continued). "A human telomerase promoter and an insulin promoter, which are controlled by PDX-1, have been used to deliver transgenes to pancreatic cancer cells." (PMID 35326649, 2022). "In this model, pancreatic cancer cells derived from the KrasLSL-G12D/+;Trp53LSL-R172H/+;Pdx1-Cre (KPC) mouse model of PDAC were injected into the pancreas of syngeneic C57/BL6 mice." (PMID 36109493, 2022). "LSL-KrasG12D Trp53lox/+ Pdx1-Cre engineered mouse models were used to investigate pancreatic cancer." (PMID 36237445, 2022). "This research frequently involves the KC (LSL:KrasG12D;Pdx1-CRE) genetically engineered mouse model, which leads to pancreatic cancer predisposition." (PMID 34302028, 2021). "Pdx-1-Cre::K-rasLSL-G12D/+::p53LSL-R172H/+::Keap1fl/fl::Nrf2+/− (KPC::K0N1) and Pdx-1-Cre::K-rasLSL-G12D/+::p53LSL-R172H/+::Keap1fl/fl::Nrf2−/−- (KPC::K0N0) mice developed invasive pancreatic cancers (2/31 and 2/17 mice, respectively) within 90 days of birth." (PMID 33672789, 2021). "PDX1 overexpression has also been observed in insulinoma, neuroendocrine tumors, and in some cases of pancreatic cancer." (PMID 34503200, 2021). "Conditional deletion of LIFR leads to reduced pancreatic tumor progression and prolonged survival in a pancreatic cancer mouse model (Pdx1-Cre; lox-stop-lox-KrasG12D/+; Trp53lox/lox; Lifrlox/lox; lox-stop-lox-Rosa26Luc/Luc)." (PMID 33572223, 2021). "To this end, we constructed one colon and four pancreatic cancer cell lines expressing PDX1 ectopically." (PMID 34503200, 2021). "Low levels of PDX1 expression were detected in the most differentiated and least mesenchymal pancreatic cancer cell line, BxPC-3." (PMID 34503200, 2021). "The increased adhesion of pancreatic cancer cells expressing PDX1 to the cationic polypeptide poly-L-lysine detected also indicates a decrease in the migration potential of cancer cells." (PMID 34503200, 2021). "Pancreatic cancer cell lines ectopically expressing PDX1 in our study had a decreased level of SERPINH1, a positive regulator of cell motility." (PMID 34503200, 2021). "A LRRC15-positive CAF subpopulation was identified in a pancreatic cancer mouse model (Pdx1-Cre; lox-stop-lox-KrasG12D/+; p16/p19lox/lox)." (PMID 33572223, 2021). "To gain an insight into the Plexin-B3 expression in the pancreatic ductal adenocarcinoma (PDAC) disease progression model, we analyzed pancreatic tumor tissues derived from the KrasG12D;Pdx1-Cre (KC) mouse model at different ages (10, 20, 30, and 50 weeks)." (PMID 33669221, 2021). "So far, most researchers have combined either Pdx1-Cre or Ptf1a-Cre mouse lines with KrasLSL-G12D mouse to develop pancreatic tumors." (PMID 33393460, 2021).
pancreatic cancer (continued). "In Pdx1-Cre; lox-stop-lox-KrasG12D/+; Ink4alox/+ murine pancreatic cancer and in pancreatic cancer patient specimens, Prrx1 is expressed in CAFs." (PMID 33333727, 2020). "Recent evidence shows PDX1 functionality and its multiple—often antagonistic—effects on pancreatic cancer are stage-specific." (PMID 33213062, 2020). "Our group has published extensively on the pro-tumorigenic role of the PDX1 transcription factor in pancreatic cancer progression, while other groups have demonstrated antimetastatic and tumor-suppressive effects." (PMID 33213062, 2020). "A recent study identified a leucine-rich repeat containing 15 (LRRC15)-positive CAF subpopulation within the PDPN-positive CAF population in pancreatic cancer mouse model (Pdx1-Cre; lox-stop-lox-KrasG12D/+; p16/p19lox/lox)." (PMID 33333727, 2020). "The interaction between obesity and PDX1 rs9581943 in our analysis suggested the involvement of metabolic disease-related pathways in the development of pancreatic cancer." (PMID 32456644, 2020). "A more recent study described the single-cell landscape of CAFs in pancreatic cancer during in vivo tumor evolution in the Pdx1-Cre;LSL-KrasG12D/+;p16/p19flox/flox (KPP) PDAC mouse model." (PMID 32752017, 2020). "While PDX1 demonstrates protective effects during certain stages of gastric and pancreatic cancer, it frequently switches from tumor-suppressor to oncogene after neoplastic transformation is complete." (PMID 33233470, 2020). "We determined the pathogenic role of IL-20 in vivo by using Pdx-1-Cre (KPC) mice, which spontaneously develop pancreatic tumors that mimic the progression of PDAC in humans." (PMID 32929072, 2020). "To investigate the possible roles of Pik3ca and Egfr in pancreatic cancer progression, we used the FC1245 pancreatic cancer cell line that was isolated from a KrasLSL–G12D/+ Trp53LSL–R172H/+ Pdx1-Cre mouse in the C57BL/6 (B6) genetic background." (PMID 31112530, 2019). "In the matured pancreas, the expression of PDX1 is restricted to insulin-producing β-cells, but is also found to be upregulated in pancreatic cancer." (PMID 31236113, 2019). "Pancreatic tumors in patients are well known for their ability to exclude T cells, and limited T cell infiltration is also a prominent feature of pancreatic tumors in KrasLSL–G12D/+ Trp53LSL–R172H/+ Pdx1-Cre mice." (PMID 31112530, 2019). "Pancreatic cancer cells revealed Pdx1‐Flp‐induced EGFP positivity and the majority of these cells also expressed CK19." (PMID 30120146, 2018). "The low expression of PDX1 in pancreatic cancer cells favors the epithelial-to-mesenchymal transition and represents a mechanism contributing to the progression in malignancy." (PMID 29156578, 2017).
pancreatic cancer (continued). "We used anti-PRR was radiolabeled with 125I, and tumor targeting was analyzed by SPECT/CT in mice bearing subcutaneous human pancreatic cancer xenografts, and genetically engineered mouse model of pancreatic cancer, Pdx1-cre; LSL-KrasG12D mice." (PMID 28874965, 2016). "We also used human pancreatic cancer mouse model, Pdx1-cre; LSL-KrasG12D mice for biodistrubution study." (PMID 28874965, 2016). "Pdx-1-cre LSL/KrasG12D/Ink4a/Arf null B6 mice always develop pancreatic cancer, allowing only 30% survival by 8 weeks, while each of the Mirk kinase inhibitor treated mice survived 8 weeks." (PMID 25352950, 2014). "Most recently, we found that DMAPT and/or sulindac in combination with gemcitabine therapy can delay or prevent progression of premalignant pancreatic lesions in the less aggressive LSL-KrasG12D/+; Pdx-1-Cre mouse model of pancreatic cancer." (PMID 23590467, 2013). "The purpose of this study was to demonstrate that PDX-1 is a therapeutic target for both hormonal symptoms and tumor volume in mouse models of pancreatic cancer, insulinoma and islet neoplasia." (PMID 22905092, 2012). "Since PANC-1 cells are human pancreatic cancer cells that markedly overexpress PDX-1, these cells were used for both in vitro and in vivo studies." (PMID 22905092, 2012). "In our xenograft mouse model of human pancreatic cancer, the most aggressive form of pancreatic neoplasia, our strategy of PDX-1 knockdown effectively reduced human pancreatic cancer tumor formation in SCID mice and prolonged survival." (PMID 22905092, 2012). "This study demonstrates that targeting PDX-1 using a novel RNAi effector platform regulates both excessive hormonal secretion, as well as reduction of tumor volume, in mouse models of pancreatic cancer, insulinoma and islet neoplasia." (PMID 22905092, 2012). "Our recent studies demonstrate that PDX-1 is an oncogene for pancreatic cancer and is overexpressed in pancreatic cancer." (PMID 22905092, 2012).
pancreatic cancer (continued). "Development of pancreatic cancer in the Pdx1-Cre KrasG12D Ink4a/Arflox/lox model involves progression from pancreatic intraepithelial neoplasia (PanINs) to pancreatic ductal adenocarcinoma (PDAC), faithfully recapitulating the human disease." (PMID 21589862, 2011). "Similarly, scRNA-seq analyses of pancreatic tumors suggested PDX1 activity reduces biosynthetic and inflammatory stress and promotes epithelial differentiation." (PMID 42064940, 2026). "Additionally, we used a KPC [C57BL/6-Krastm1(LSL-G12D)Trp53tm1(LSL-R172H)Tg(Pdx1-Cre)] transgenic mouse model, which spontaneously develops pancreatic cancer, and administered a combination of D166 and anti-PD-1." (PMID 40520004, 2025). "Moreover, we generated control and Bap1 knockout KPC (KrasG12D/+; LSLTrp53R172H/+; Pdx-1-Cre) mouse pancreatic cancer cell lines and established the mouse syngeneic subcutaneous pancreatic cancer model." (PMID 39350280, 2024). "To further identify roles of MFAP5 in CAFs, we extracted and cultured human primary CAFs (CAF3) derived from the PDAC patient, and mouse primary CAF cell line (ImdyCAF) derived from spontaneous pancreatic tumors in transgenic mouse (KrasLSL-G12D, Trp53LSL-R172H, Pdx1-Cre (KPC) mice)." (PMID 37156839, 2023). "As our tumor cell models, we have employed the commonly used cell line Panc02, a model established by the direct exposure into the pancreas of C57BL/6 mice with 3-methyl-cholanthrene, and the cell line UN-KC-6141, derived from the pancreatic tumor of a KrasG12D; Pdx1-Cre (KC) mouse." (PMID 37572121, 2023). "For example, in pancreatic cancer, PDX-1 expression may de-differentiate tumor cells with more aggressive states." (PMID 35892853, 2022). "Here, we examined whether chronic ethanol treatment induces epithelial–mesenchymal transition in HPNE cells and promotes pancreatic cancer development in KC (Pdx1‐Cre, and LSL‐KrasG12D) mice." (PMID 34859959, 2022). "However, conditional deletion of Shh results in more aggressive, undifferentiated tumors in a pancreatic cancer mouse model (Pdx1-Cre; lox-stop-lox-KrasG12D/+; Trp53lox/+; Shhlox/lox; lox-stop-lox-YFP-Rosa26)." (PMID 35159011, 2022). "Since KC mice mimic pancreatic cancer development in humans, we have used this model to examine whether ethanol promotes pancreatic cancer growth and development in KC (Pdx1‐Cre, and LSL‐KrasG12D) mice." (PMID 34859959, 2022). "LSL-KrasG12D Trp53lox/+ Pdx1-Cre mice developed a well differentiated pancreatic cancer." (PMID 36237445, 2022).
pancreatic cancer (continued). "In this study, b175ased on previously obtained data, we studied the effect of PDX1 expression on the proliferative and migratory capabilities of four pancreatic cancer cell lines (BxPC-3, Colo357, MiaPaCa-2, and PANC-1) and the colon cancer line SW620 in vitro." (PMID 34503200, 2021). "In order to establish a link between MUC4 and miR-210-3p in early-stage PDAC, we evaluated miR-210-3p expression level by RT-qPCR and Muc4 immuno-staining scores by immunohistochemistry (IHC) in Pdx1-Cre; K-rasG12D (KC) transgenic mouse model of pancreatic cancer." (PMID 34944818, 2021). "One of the limitations of this study is the use of Pdx1-Cre in the modeling of pancreatic cancer." (PMID 33268505, 2021). "We also isolated bone marrow neutrophils from the KPC mouse model (KrasLSL-G12D/+;Trp53LSL-R172H/+;Pdx1–Cre) with pancreatic tumors and demonstrated that FES was among the group of kinases with significant increased activity compared to neutrophils from tumor-free control mice." (PMID 34099731, 2021). "Expanding on our previous findings, we have shown that ectopic expression of the pancreatic lineage specifier PDX1 reduces the migration potential of pancreatic cancer cells by increasing their adhesiveness and reducing the sensitivity to TGFβ1-induced epithelial-mesenchymal transition." (PMID 34503200, 2021). "For this, we tested mouse pancreatic cancer cell lines derived from a Pdx1-cre;KrasLSL.G12D/+;Tp53LSL.R172H/+ mouse model (KPC), which has been further modified to obtain the Zeb1 knockout, called KPCZ, to show a role of Zeb1 in the metastatic cascade of pancreatic tumors." (PMID 33654197, 2021). "We were able to show the significant interaction between poor oral hygiene and NR5A2 rs2816938 and between obesity and PDX1 rs9581943, which suggested the involvement of inflammation and metabolic disease-related pathways in the development of pancreatic cancer." (PMID 32456644, 2020). "However, conditional deletion of Shh (Shhlox/lox) reduces stromal content, but tumors are more aggressive, undifferentiated, and display increased vascularity in the Pdx1-Cre; lox-stop-lox-KrasG12D; Trp53lox/+ pancreatic cancer mouse model." (PMID 33333727, 2020). "In an orthotopically transplanted mouse model using pancreatic cancer cells isolated from tumors of transgenic KrasLSL-G12D/+, Trp53LSL-R172H/+, Pdx1-Cre (KPC) mice that express PD-L1, tumors were sensitized to anti-PD-1/PD-L1 therapy in response to cabozantinib-depleted PMN-MDSCs." (PMID 33348809, 2020). "Similarly, INCB057643 modified immune cell populations in the pancreas of KrasG12D/+; Pdx-1-Cre (KC) mice with pancreatitis, an inflammatory process known to promote pancreatic cancer progression." (PMID 33396954, 2020). "To investigate the role of Hmga2 in PDAC, we first confirmed Hmga2 expression in the carcinoma stage of pancreatic cancer tissue isolated from the well-established autochthonous KrasLSL-G12D/+;p53LSL-R172H/+;Rosa26LSL-tdTomato/+;Pdx1-Cre (KP172CT) mouse model of PDAC." (PMID 30228296, 2018).